CD68 (CD68 molecule)
Diseases named in the same sentence as CD68 in open-access papers (continued):
Sharing a sentence is not in itself a finding about the gene and the disease.
ischemia (26 papers, 2011 to 2024). A hypoperfusion of the BLOOD through an organ or tissue caused by a PATHOLOGIC CONSTRICTION or obstruction of its BLOOD VESSELS, or an absence of BLOOD CIRCULATION. "It is indicative of phagocytic activity and is upregulated in response to pro-inflammatory stimuli linked to conditions like ischemia and aging where CD68 is also associated with lipofuscin accumulation in microglia." (PMID 38388518, 2024). "Immunofluorescence images (Figures 7A3−D3) illustrate a line-like morphology in the co-staining of CD68 with Iba-1 on days 4 and 7, potentially indicating the accumulation of CD68 around microvasculature injured by ischemia, which is associated with phagocytic functions." (PMID 38075277, 2023). "In this study, the activation of phagocytic microglia after ischemia was suppressed by cortical ES, as presented by the decreased number of Iba1/CD68-positive cells in the ischemic penumbra of the cerebral cortex." (PMID 34867274, 2021). "At 12 (3.88-fold expression, p < 0.001) and 24 h (2.61-fold expression, p = 0.008), as well as at 3 (27.49-fold expression, p < 0.001) and 7 days (16.15-fold expression, p = 0.001), Cd68 expression was significantly upregulated in the ischemia group." (PMID 32833183, 2021). "As PGZ inhibited the expression of CD16+/CD68+ M1-like macrophages in our rats, we think that in the early phase of post-ischemia, it inhibited the recruitment of M1-like monocyte-derived macrophages from the perivascular area into the brain." (PMID 29110250, 2018). "In comparison to the brain, the heart infarcts contained markedly more collagen and substantially fewer T-lymphocytes, B-lymphocytes, and CD68+ macrophages at four and eight weeks following ischemia." (PMID 30417081, 2018). "Equally, CD68 mRNA (activated microglia) expression was significantly increased in the ischemia (2.824 expression ratio; p = 0.009) and in the ranibizumab groups (2.742 expression ratio; p = 0.004) in relation to controls." (PMID 28800629, 2017). "Macrophage infiltration was also reduced in the brain after ischemia, which was validated by immunostaining of CD68+ macrophages in the brain." (PMID 26873581, 2016). "To quantitatively describe the temporal evolution of microglia activation following striatal ischemia, we counted the number of CD68+ cells between 3 and 30 PLDs." (PMID 28090244, 2016). "Iba1+ and CD68+ cells infiltrated around the damaged myelin after MCAO, the result suggested that these cells were implicated in ischemia-induced myelin lesion." (PMID 26873581, 2016). "In the eyes with ischemia, on the other hand, distinct protein bands corresponding to Iba1 and CD68 were found with molecular weights of 17 kDa and 75–110 kDa, respectively." (PMID 27259948, 2016). "In addition, the total number of cells labeled by CD68 or CD206 (inflammatory/anti‐inflammatory microglia) also gradually increased within 7 days after ischemia in the lesioned hemisphere." (PMID 39252446, 2024). "First, we measured the microglial activity of mice exposed to CRM28 by IHC of Iba1 and CD68 in the olfactory bulb and cerebral cortex because the olfactory bulb is considered to be first target of PM nasally administrated and because ischemia is induced in the cerebral cortex." (PMID 36797786, 2023). "Notably, cerebral ischaemia enhanced CD68 expression (CD68H) in MG, and our results showed that the frequency of CD68H MG was significantly higher in the ipsilateral hemisphere of IRG1−/− MCAO mice than that of WT MCAO mice." (PMID 34557667, 2021). "Immunofluorescence with conformation specific detection of CRP and CD68+ cells in striated human muscle tissue shortly before (pre-ischemia) and after free tissue transfer (post-reperfusion) revealed extensive deposition of neo-epitope expressing CRP in the IRI-challenged tissue." (PMID 29713320, 2018).
ischemia (continued). "In addition, more activated CD68+ microglia were detected in the ischemia (5.1±0.7 cells/mm; p<0.001) and the ranibizumab groups (7.7±1.1 cells/mm; p<0.001) when compared to the control group (0.3±0.1 cells/mm)." (PMID 28800629, 2017). "Here, we investigated activated microglia using CD68/Iba-1 double-staining after BCAS hypoperfusion, as microglial activation is a key element in initiating and perpetuating inflammatory responses to ischemia." (PMID 37917300, 2024). "Previously, we found that in the ischemia brain cortex of dMCAO model, IGF-1 was partially expressed by NeuN+ neurons and CD68+ microglia/macrophages." (PMID 32952570, 2020). "Other cell types, such as CD68+ microglia, and NeuN+ neurons, are partly responsible for production of BDNF, even after the induction of ischemia." (PMID 30405724, 2018). "We observed an up-regulation of the CD68-positive microglia sub-population and a down-regulation of the TMEM119-positive microglia sub-population after ischemia which is in line with numerous other studies investigating microglial cell activation after brain lesions." (PMID 39272984, 2024). "In AAV_EGFP-treated eyes, we detected a clear microglial activation with elevated CD68 levels after ischemia compared to non-ischemic controls." (PMID 38388518, 2024). "Some CD68+ cells were also detected in the white matter of the hemisphere contralateral to ischemia (data not shown)." (PMID 21599903, 2011).
aneurysm (25 papers, 2009 to 2025). Bulging or ballooning in an area of an artery secondary to arterial wall weakening. "Cells that are CD68+, a marker for macrophages and monocytes, are found in both human and rodent aneurysm tissue, and their abundance correlates with pathogenic wall remodeling." (PMID 41541085, 2023). "Positive effects for CD68 were associated with higher prevalence of female patients, ruptured aneurysms, and subarachnoid hemorrhage." (PMID 37744724, 2023). "VSMCs, myofibroblasts, and fibroblasts acquired phagocytic markers LAMP2 and CD68 proportionally to the severity of aortic disease, and cells from dissecting aneurysms were positive for Ter-119, suggesting an association with red blood cells." (PMID 30943775, 2019). "It is important to note that no statistical correlation (p = 0.67) was found between SAH, familial history of aneurysms, and activation of CD68+." (PMID 37744724, 2023). "A total of 13 patients were identified showing positive effects for CD68 due to the composition of the aneurysm wall." (PMID 37744724, 2023). "In recent times, it has been highlighted by various authors that the percentage of CD68-positive cells in recently ruptured aneurysm domes (within 2 days) is significantly higher compared with the percentage in unruptured aneurysm domes." (PMID 37744724, 2023). "In order to evaluate the localization of ADAMTS4, SMCs, and CD68 + cells within the aneurysm, immunofluorescence analysis of 10 μm thick AAA cryosections after 4 weeks of AngII-infusion was performed." (PMID 35606349, 2022). "To confirm the atherosclerotic inflammation, we noticed a comparable level of CD3+ T cells in both aneurysms and a raised level of CD68+ macrophages in BBAs." (PMID 35874788, 2022). "Because FcγR colocalized with CD68+ macrophages in human and mouse aneurysm, we further analyzed the specific role of monocyte/macrophage FcγR activity in AAA." (PMID 34323424, 2021). "Nevertheless, immunohistochemistry revealed CD3+ T cells and CD68+ macrophages that were more frequent in aneurysms than in normal aorta, as in our case." (PMID 33807627, 2021). "The CD68-positive cell rate in the elastase-induced aneurysms is significantly lower than that in normal aneurysms, proving that the inflammatory mediators affect the onset of aneurysms through monocytes/macrophages." (PMID 32908904, 2020). "As the figure shows, the number of CD68 positive cells from group A to group E aneurysm wall increased significantly." (PMID 27965979, 2016). "Notably, the levels of serum IL-1β and IL-1.ra were correlated with the relative levels of GSDMD, MMP2 and CD68 in aneurysm tissues." (PMID 35155635, 2022). "Importantly, aneurysm tissue harvested from patients infused with ferumoxytol stained positive for CD68 and Prussian blue while tissue harvested from controls stained positive for CD68 but not for Prussian blue." (PMID 23945642, 2013). "Genes that can be considered as markers for the following cell types were upregulated in aneurysms: neutrophils (Csf3r); T lymphocytes (Cd3d) and B lymphocytes (Blnk, Cd72, various immunoglobulin genes); and monocyte/macrophages (Cd14, Cd68)." (PMID 19580648, 2009). "Our histological stainings of AAA tissue confirmed that RNase A treatment was accompanied by reduced CD68+ macrophage infiltration, and neutrophil markers such as MPO tended to be decreased in gene expression analysis of RNase treated mouse aneurysms." (PMID 41173972, 2025). "RNA FISH indicated that a spot of cells coexpressing αSMA and CD68 and a spot of cells coexpressing αSMA and CD3D were present in the tunica media of aneurysm tissue, verifying the presence of macrophage-like VSMCs and T-cell-like VSMCs." (PMID 37189183, 2023).
aneurysm (continued). "Histological analysis (such as SMA-α, CD31, CD34, CD68, collagen IV, and Ki67) and the other relevant indexes were compared between the ideal model's aneurysmal tissues and the human intracranial aneurysm's tissues to confirm whether we have successfully established elastase-induced aneurysm models." (PMID 32908904, 2020). "Methods and Results: Human aneurysm tissues were collected by microsurgical clipping and immunostained for phospho-Focal adhesion kinase (FAK) and CD68+ macrophages." (PMID 29899701, 2018). "The immunohistochemical staining was used to analyze the infiltration of pro-inflammatory (CD68) and anti-inflammatory macrophages (CD163), T helper (CD4) and T killer cells (CD8), and B (CD79a) and plasma cells (CD138) in all three layers of aneurysms of both groups." (PMID 34656077, 2022). "In the in vivo study, we detected a gross lower expression level of CD68 and ARG1 (macrophage), Aggrecan (chondrocyte), OPN (osteoblast), ADIPQ (adipocytes), CD34 (mesenchymal cells), and LUM (fibroblasts) in the FAM3A-overexpressing aneurysm tissues compared with the matched Ad-sham tissues." (PMID 37660071, 2023). "The aneurysm prone aortic tissues of the DMSO-treated mice contained PI-positive necrotic cells, elevated levels of phospho-MLKL, as well as terminal deoxynucleotidyl transferase dUTP nick end labeling (TUNEL)-positive apoptotic cells and CD68-positive macrophages." (PMID 30842407, 2019). "Both autophagy factors also co‐localized with CD68+ cells and S100A4+ cells in murine aneurysm tissue; however, we chose not to further pursue these cell types in the in vitro analysis (data not shown)." (PMID 31025534, 2019). "Also, when testing for cell subsets, ruptured and non-ruptured aneurysms exhibited similar numbers of CD68+CD206− M1 and CD68+CD206+ M2 macrophages (p=0.206), CD3+CD8+ cytotoxic T cells (p=0.329), CD3+CD8−FoxP3+ regulatory T cells (p=0.206), and CD3+CD45RO+ memory T cells (p=0.176)." (PMID 35137689, 2022).
ischemic stroke (24 papers, 2013 to 2025). A stroke disorder caused by obstruction of blood flow to the brain, due to thrombotic (local blood clot formation) or embolic (due to a blood clot or other material traveling from another site) event. "We show that compared with 2-month-old mice, the 12-month-old mice had reduced functional recovery after ischemic stroke, which was associated with the increase in the number of CD68+ macrophage/microglia, and higher inflammatory cytokines levels." (PMID 30705764, 2019). "Using rat models of ischemic stroke, researchers have found that CD68 expression is a reliable indicator of microglial activation." (PMID 37569457, 2023). "CD68 expression also increased 1 day after ischemic stroke, clearly indicating ischemic activation of microglia." (PMID 36797786, 2023). "To explore the effect of 4-EG on MG activation in ischemic stroke, we measured the expression of maturation markers, CD68 and CD86, on MG." (PMID 35860274, 2022). "In order to further investigate the potential role of Dectin-1 in ischemic stroke, microglial activation was assessed by Iba-1 and CD68 staining, and the expression of inflammatory cytokines was examined via western blotting." (PMID 31926564, 2020). "CD68+ cells were detected at 1 day after ischemic stroke in the brains of both old and young mice, which peaked at 3 days, and were still present at 14 days after dMCAO." (PMID 30705764, 2019). "We also demonstrated that the old mice had more CD68+ cells than the young mice after ischemic stroke." (PMID 30705764, 2019). "We first analyzed if clenbuterol treatment after ischemic stroke altered macrophage activation and/or numbers in the cortex by immunostaining for CD68, a marker for activated microglia and macrophages." (PMID 31138227, 2019). "Immunohistochemical staining, as well as immunofluorescence confocal imaging, of post-mortem tissues from subjects who had suffered an ischemic stroke, was used with a CD68-antibody to detect activated myeloid cells." (PMID 27566702, 2016). "To characterize MANF protein expression in the infarcted human brain, we utilized immunohistochemistry for MANF and CD68 in consecutive postmortem tissue sections of patients deceased approximately 3 days, 1 week and 2 weeks after ischemic stroke (n = 2–3 per time point)." (PMID 38229173, 2024). "Notably, ischemic stroke enhanced the microglial expression of CD68 (CD68H) in the ipsilateral hemisphere of the ischemic brain." (PMID 35860274, 2022). "The numbers of CD68+ cells were significantly increased in the peri-infarct area in old mice 2 weeks after ischemic stroke, indicating that aging might impair the resolution of inflammation." (PMID 30705764, 2019). "CD68 is specifically expressed in microglia in ischemic stroke brain." (PMID 29209166, 2017). "Furthermore, we demonstrate that MG-specific Nrf2 knockdown results in attenuated endogenous Nrf2/HO-1 axis activation, leading to suppressed CD206 expression and enhanced CD68 expression in MG, and that subsequently aggravates neuroinflammation and exacerbates brain injury in ischemic stroke." (PMID 39469715, 2024). "Following MCAO in rats and mice, hypertrophic, CD68-positive mononuclear phagocytes, arising from both activated microglia and infiltrating monocytes become abundant in the infarcted area and the penumbra between 18 and 96 h after an ischemic stroke and have been described to peak between 7–14 days." (PMID 37180699, 2023). "MANF expression colocalized with GRP78 in CD68-positive cells, indicating UPR activation in microglia/macrophages after ischemic stroke." (PMID 35783104, 2022). "Indeed, when we analysed the ischaemic brain of WT and IRG1−/− MCAO mice, we found increased CD68+ MG and CD86+ MG as well as elevated Iba1+ cells in the ischaemic brain of IRG1−/− MCAO mice compared to WT MCAO mice, demonstrating IRG1 deficiency promotes MG activation in ischaemic stroke." (PMID 34557667, 2021).
ischemic stroke (continued). "Blood-derived monocytes (Ccr2+CD68–), inflammatory macrophages (Ccr2+CD68+) and activated perivascular macrophages (CD206+CD68+) in the perivascular space are present in the cortical ischemic stroke area within the first days after PT, coinciding with massive fibrinogen deposition." (PMID 41280671, 2025). "However, in ischemic stroke, we have reported that MANF induced a transient increase in CD68-positive innate immune cells, which is likely beneficial for tissue repair." (PMID 35783104, 2022). "Furthermore, as anticipated, our study established that VNS treatment could reduce the transformation of microglia to pro-inflammatory reaction (CD68+Iba+) and promote its stabilization in anti-inflammatory reaction (CD206+Iba+) after ischaemic stroke, similar to the findings in other studies." (PMID 37153558, 2023). "Altogether, our results demonstrate that ischemic stroke induces comparable levels of HO-1, CD206, and CD68 expression in MG in the ischemic brains of female and male MCAO mice, suggesting sex does not affect ischemia-induced MG phenotypes after ischemic stroke." (PMID 39469715, 2024).